LAGE3 (L antigen family member 3)
Diseases named in the same sentence as LAGE3 in open-access papers (continued):
Sharing a sentence is not in itself a finding about the gene and the disease.
tumor (10 papers, 2020 to 2023). "On analyzing the relationship between LAGE3 and the clinicopathological features in the local cohort, we found that large tumor size (p = 0.0127) was significantly associated with high LAGE3 expression." (PMID 33552947, 2020). "In addition, multivariate analysis indicated that “age” and “tumor stage” were significantly associated with high-risk factors, and LAGE3 expression levels are an independent survival determinant in patients with BRCA." (PMID 33921749, 2021). "Taken together, these results suggested that LAGE3 might be linked with tumor development, metabolism, and immune activity in BC." (PMID 33552947, 2020). "When we investigated the correlation between LAGE3 expression and clinicopathological factors in BC, we noticed that the up-regulation of LAGE3 was associated with the higher T stage, more metastatic lymph nodes, higher tumor grades, and more advanced disease stages." (PMID 33552947, 2020). "High expression of LAGE3 was significantly correlated with T stages, pathologic stages, tumor status, and vascular invasion (–D)." (PMID 35433409, 2022). "Studies have found that LAGE3 was overexpressed in multiple tumor tissues compared with normal tissues." (PMID 35433409, 2022). "We first assessed the expression of LAGE3 in multiple tumor and normal tissue types using the Oncomine database." (PMID 35433409, 2022). "Since Huh7 cells transfected with siLAGE3 or siCtrl were subcutaneously inoculated into BALB/c nude mice in vivo, LAGE3 knockdown lessened the volume and weight of tumor tissues, respectively." (PMID 35313850, 2022). "Accordingly, the results from the subcutaneous tumor-bearing mice models showed the lentivirus-mediated silencing of LAGE3 by shRNA reduced tumor volumes and weights, compared to the lenti-NC mice (–D)." (PMID 35433409, 2022). "Nevertheless, since we used a small sample size to verify the predictive value of LAGE3 as a biomarker in CM, there is a need for the inclusion of more tumor samples or cohorts for the Cox regression analysis." (PMID 33829062, 2021). "In the multivariable Cox regression analysis, age, tumor size (T), regional lymph nodes (N), radiation therapy, and LAGE3 expression were statistically significant prognostic factors for OS and DSS in the metastatic CM." (PMID 33829062, 2021). "We exploited Gene Ontology (GO), Kyoto Encyclopedia of Genes and Genomes (KEGG), and Gene Set Enrichment Analysis (GSEA) to dissect the functional roles of LAGE3 in tumor-infiltrating immune cells (TIICs) in the tumor microenvironment (TME)." (PMID 33829062, 2021). "Subsequent univariate Cox regression analyses revealed that tumor size, LNM stage, tumor grade, disease stage, ER, PR, HER2, and LAGE3 expression were associated with OS and DSS." (PMID 33552947, 2020). "In the TCGA dataset, we observed an incremental change in the LAGE3 mRNA levels with larger tumor size, more metastatic lymph nodes, and higher disease stages (all p < 0.05)." (PMID 33552947, 2020). "We further used the TIMER database to verify how LAGE3 expression differed in specific tumor types." (PMID 35433409, 2022). "Lastly, it was stated that LAGE3 might promote tumor development in HCC via PI3K/AKT/mTOR and Ras/RAF/MAPK pathways." (PMID 35313850, 2022). "We then examined the LAGE3 expression pattern in the tumor and normal tissues." (PMID 33829062, 2021). "Indeed, previous studies demonstrated LAGE3 expression in other tumor cells, which is consistent with our findings." (PMID 33921749, 2021). "This evidence suggested that the LAGE3 protein could lead to the dysregulation of TIICs in tumor sites." (PMID 33829062, 2021). "Similarly, it was observed that LAGE3 knockdown could inhibit the migration, invasion, and cause apoptosis induction in HCC cells and effectively inhibit the growth of tumor tissues in vivo." (PMID 35313850, 2022).
tumor (continued). "An analysis of the survival data revealed that a LAGE3 overexpression was associated with a poor prognosis of OS (p = 0.001) and DFS (p = 0.019), while the Gene Expression Profiling Interactive Analysis 2 (GEPIA) database tool also confirmed that LIHC tumor tissues highly expressed LAGE3." (PMID 35313850, 2022). "Besides, our study revealed a markedly negative correlation between LAGE3 and immune infiltration; thus, the potential biological mechanisms of LAGE3 should be systematically investigated using both in vivo models and in vivo experiments for tumor-immune interaction analysis." (PMID 33829062, 2021). "Furthermore, validation of our coculture experiments using AFP specific TCR-T cells showed that knockdown of LAGE3 in HepG2 cells could increase the sensibility of tumor cell death induced by cytotoxic T cells and the ability of cytokine secretion of cytotoxic T cells." (PMID 35433409, 2022). "We also identified Gm6890, a human ortholog of LAGE3 and a core component of the KEOPS complex, amongst the top upregulated genes across the analyzed time frame of tumor development." (PMID 34638267, 2021). "As a validation, we found that there were statistically significant differences in LAGE3 expression between different LNM stages, tumor grades, and disease stages in the METABRIC dataset (all p < 0.05)." (PMID 33552947, 2020). "Our study results displayed that since LAGE3 might promote tumor development in HCC via PI3K/AKT/mTOR and Ras/RAF/MAPK pathways, the development of LAGE3 target drugs may be a new treatment strategy for HCC patients." (PMID 35313850, 2022). "Similarly, our study also found that the levels of LAGE3 gene and protein expression were significantly higher in HCC tumor tissues than in normal tissues through public online tools." (PMID 35433409, 2022). "In conclusion, it could be stated that LAGE3 has prognostic prediction value and may influence HCC tumor progression by promoting the proliferation, survival, migration, invasion, and anti-apoptotic ability of HCC cells through PI3K/AKT/mTOR and Ras/RAF/MAPK pathways." (PMID 35313850, 2022). "Besides, LAGE3 was also involved in regulating numerous biological functions of HCC cell lines, including proliferation, apoptosis, migration, invasion, the sensitivity of tumor cell death." (PMID 35433409, 2022). "Functionally, knocking down LAGE3 expression not only increased apoptosis and inhibited growth rate, cell death mediated by T cells, colony formation, migration and invasion ability of HCC cell lines in vitro, but also reduced the progression of HCC in the subcutaneous xenotransplanted tumor model." (PMID 35433409, 2022).
neurodegenerative disease (1 paper, 2020). A disorder of the central nervous system characterized by gradual and progressive loss of neural tissue and neurologic function. "LAGE3 was closely associated with several neurodegenerative diseases, which were also consistent with previous research." (PMID 33552947, 2020).
LAGE3 also shares sentences with these, for which no sentence is quoted: infection (4 papers); nephrotic syndrome (3); Primary microcephaly (2); brain disorder (1); cervical squamous cell carcinoma (1); cholangiocarcinoma (1); clear cell renal cell carcinoma (1); colon adenocarcinoma (1); esophageal carcinoma (1); fungal infection (1); fungal meningitis (1); Galloway-Mowat syndrome 1 (1); head and neck squamous cell carcinoma (1); Huntington disease (1); kidney cancer (1); leukemia (1); lung adenocarcinoma (1); lung carcinoma (1); lung squamous cell carcinoma (1); lymphoma (1); myeloma (1); nevus (1); Parkinson disease (1); prostate adenocarcinoma (1); rectum adenocarcinoma (1); sarcoma (1); stomach adenocarcinoma (1); thyroid carcinoma (1); uterine corpus endometrial carcinoma (1).